LDHA (lactate dehydrogenase A)
Diseases named in the same sentence as LDHA in open-access papers (continued):
Sharing a sentence is not in itself a finding about the gene and the disease.
cancer (continued). "The association between high expression of LDHA and prognosis of pan-cancer in TCGA database." (PMID 38709280, 2024). "The level of LDHA expression was significantly associated with a poor prognosis in cancer patients." (PMID 37298317, 2023). "The Warburg effect (aerobic glycolysis) of cancer cells contributes to the accumulation of lactate, which is associated with the activity of several major glycolytic enzymes, especially lactate dehydrogenase A (LDHA)." (PMID 36737430, 2023). "The strong association with LDHA suggests that this enzyme isoform may be involved in a key mechanism for cancer progression." (PMID 37684649, 2023). "Notably, the induction of PKM2 and LDHA is moreover a hallmark of the Warburg effect in cancer cells, which is also induced by the elevation of TH signal in cancer." (PMID 37569453, 2023). "LDHA, a rate-limiting enzyme in glycolysis, mediates immune escape by regulating lactate production, promotes cell proliferation, is highly expressed in various cancers, and has been implicated in the progression and prognosis of the OE." (PMID 36212136, 2022). "Furthermore, lactate dehydrogenase A (LDHA) expression is upregulated in many cancers where it is associated with more aggressive disease and survival of cancer-initiating cells." (PMID 35362044, 2022). "LDHA is an enzyme that catalyzes the mutual conversion of pyruvate and lactic acid, as well as promotes invasion, metastasis, nest loss, and apoptosis resistance in various cancers." (PMID 34869590, 2021). "As our results suggest an important role of the glycolytic pathway in the drug-sensitive A549 cells, we focused on the potential role of LDHA (Lactate dehydrogenase A) being the primary metabolic enzyme that converts pyruvate to lactate in cancer cells and a hallmark of aggressive cancers." (PMID 34066944, 2021). "Mutations in LDHA were widespread in different cancers, including BLCA." (PMID 34743698, 2021). "We show that CA IX is required for full expression and activity of a key glycolytic enzyme LDHA, while reduced expression or inactivation of CA IX in hypoxia-exposed cancer cells results in loss of control over intracellular pH, decreased glycolytic flux and reduced cell proliferation." (PMID 32983978, 2020). "LDHA is the key enzyme in the Warburg effect, which is a hallmark of cancer." (PMID 32859246, 2020). "Furthermore, the cancer- and grade-dependent increases in lactate concentration in biopsies correlated with mRNA expression of LDHA, the gene that encodes the LDH enzyme subunit with the highest affinity for reduction of pyruvate to lactate." (PMID 32110965, 2020). "In addition, transgenic mice with targeted LDHA K222E mutation need to be constructed and applied in murine models of cancer to further explore the role of K222E mutation." (PMID 32859246, 2020). "In a similar manner, elevated aerobic glycolysis is observed in many cancers, and many cancers are associated with elevated expression of LDHA, responsible for conversion of pyruvate to lactate at the last step of glycolysis and regulated by HIF1-alpha signaling amongst others." (PMID 31843010, 2019). "Deregulation of LDHA has been reported in many cancers, but the underlying biochemical process by which LDHA acts on cancer cells has been unknown." (PMID 30688660, 2019). "Moreover, LDHA-associated lactic acid production leads to a relatively low pH, allowing cancer cells to survive immune evasion via diminishing nuclear factor of activated T cells (NFAT) levels and T and NK cell activation." (PMID 30688660, 2019). "Therefore, overall, these data indicate that LDHA plays a pivotal role in the metabolic rewiring that underlies cancer cells’ acquired resistance to NAMPT inhibition in our models." (PMID 29541451, 2018). "The cancer associated LDHA isoform was inhibited with IC50 = 117–174 μM." (PMID 29199484, 2018).
cancer (continued). "LDHA encodes an enzyme that catalyzes the conversion of pyruvate to lactate, and has been involved in the Warburg effect (or anaerobic glycolysis), which is the propensity of cancer cells to take up glucose avidly and convert it to lactate." (PMID 28027290, 2016). "High LDHA levels have been linked to poor prognosis in many cancer lineages." (PMID 24280423, 2013). "We performed differential expression testing to found that cluster C3 over-expresses ENO1, BNIP3, PGK1 and LDHA, 4 genes associated with hypoxia (absolute log fold change above 0.5 and Wilcoxon test p-values below 0.01), that have been previously associated with cancer progression." (PMID 37917660, 2023). "In this study, we modeled the mechanism of resistance to the LDHAi oxamate, aiming to understand the mechanisms underlying cancer cell adaptation to glycolysis and LDHA inhibition, which may lead to improved glycolysis targeting and LDHAi–based cancer therapies." (PMID 35982980, 2022). "Also, LDHA inhibition causes reduced cancer cell proliferation." (PMID 25228990, 2014). "At the mechanistic level, extended analyses revealed divergent cellular responses to LDHA inhibition between cancer models, particularly in pathways related to hypoxia, ER stress, and redox homeostasis." (PMID 41554705, 2026). "Lactate dehydrogenase A (LDHA), a key glycolytic enzyme, has been implicated in the progression and metastasis of various cancers." (PMID 42240603, 2026). "High lactate levels favor M2-like polarization, linking LDHA overexpression to both metabolic and immune suppression in cancer." (PMID 40433363, 2025). "In a study investigating the anticancer effects of FX11, the LDHA enzyme was found to be essential for cancer progression." (PMID 40091035, 2025). "While prior studies have focused on transcriptional and translational control of LDHA, post‐translational regulation by modifications such as methylation remain less explored in cancer." (PMID 41163796, 2025). "It is assumed that ULK1 phosphorylates LDHA in muscle and cancer cells under these conditions, thereby increasing LDHA activity and promoting the production of lactate." (PMID 40357169, 2025). "MDSCs cocultured with TTN-deficient cancer cells transfected with a stable TTN-knockout plasmid increased glycolytic markers such MCT4, GLUT4, and LDHA." (PMID 41326912, 2025). "Recent studies have shown that during the development of HCC, local hypoxia drives the evolution of cancer cell subsets into a cell lineage with high lactate dehydrogenase A (LDHA) expression." (PMID 40153584, 2025). "Inhibition of LDHA by oxamate reduced H3K18la levels and circumvented immune evasion of cancer cells by enhancing CD8+ T-cell cytotoxicity." (PMID 40535811, 2025). "Studies have also shown that LDHA is necessary for the transformation induced by c‐myc in cancer cells." (PMID 39778006, 2025). "In glycolytic cancer cells, LDHA produces lactate from pyruvate and MCTs, coupled to their chaperone CD147, export lactate produced by glycolysis, which then acts in an autocrine/paracrine fashion to activate GPR81." (PMID 41375220, 2025). "H19 was found to enhance cancer cell proliferation and glycolysis by downregulating miRNA-519d-3p and upregulating LDHA, highlighting its potential as a therapeutic target." (PMID 40861865, 2025). "Developing selective LDHA inhibitors with robust in vivo efficacy remains a promising strategy for cancer therapy." (PMID 40734168, 2025). "LDHA expression was also observed in normal cells in 12/260 (4.62%) cases adjacent to cancer tissues." (PMID 41368023, 2025). "Previous reports have shown that LDHA inhibition can trigger apoptosis via ATP depletion and reactive oxygen species accumulation in cancer cells." (PMID 40565174, 2025). "Glycolytic enzymes such as LDHA, PKM2, HK2, and ENO1, along with nutrient transporters like GLUT1, ASCT2, and LAT1, are consistently upregulated across multiple cancer types and have been linked to poor prognosis and therapy resistance." (PMID 41154605, 2025).
cancer (continued). "For instance, the inhibition of LDHA using oxamate significantly enhances radiosensitivity in cancer cells, leading to increased apoptosis and autophagy following ionizing radiation (IR)." (PMID 40535811, 2025). "Inhibiting LDHA with GSK2837808A (GSK, an LDHA inhibitor) effectively blocks aerobic glycolysis in cancer cells, creating a high-glucose, low-lactate environment." (PMID 40535811, 2025). "Given the high proliferation rate and the high production of ROS in cancer cells, LDHA nuclear translocation is an effective way to balance aberrant proliferation and oxidative stress injury." (PMID 40710803, 2025). "This suggests a potential functional role for nuclear LDHA in mitigating oxidative stress and supporting cell cycle re-entry in stressed cardiomyocytes, potentially analogous to its role in cancer survival." (PMID 40710803, 2025). "Lactate dehydrogenase A (LDHA), a predominant enzyme in aerobic and anaerobic glycolysis, plays a pivotal role in supporting the energetic and biosynthetic demands of cancer cells." (PMID 40390151, 2025). "Essential targets in therapeutic targeting of cancer metabolism are glycolytic enzymes, including LDHA, PKM2, HK2, ALDOA, G6PD, PPP cycle, glutamine serine metabolism and pyruvate oxidation." (PMID 40076506, 2025). "A 2021 study investigated the regulation of lactate dehydrogenase (LDHA), a novel biomarker for cancer prognosis, and its role in supporting the growth and metastasis of papillary thyroid tumors by mediating glycolysis." (PMID 40149464, 2025). "Cancer cells express high level of LDHA to increase the rate of aerobic glycolysis, lactate and ATP production for rapid cell proliferation, which benefits cancer cells by avoiding the generation of oxidative stress." (PMID 39930542, 2025). "LDHA is essential for increased glycolysis and oncogenic functions in cancer cells and is a transcriptional target of the oncogene MYC, which provides molecular regulation for the Warburg effect." (PMID 40734168, 2025). "LDHA inhibitors offer a promising avenue for targeting the metabolic vulnerabilities of cancer cells, particularly in tumors characterized by high glycolytic flux and lactate production." (PMID 40948941, 2025). "Nuclear LDHA has been observed in several cancer types, where its ROS-induced translocation enhances antioxidant capacity, facilitating survival and proliferation under oxidative stress." (PMID 40710803, 2025). "Clinically, high LDHA expression correlates with increased metastasis and poor outcomes in cancer patients, highlighting its potential as a prognostic biomarker and therapeutic target." (PMID 41163796, 2025). "LDHA is involved in the deteriorative progression of cancers via regulating multiple cellular mechanisms." (PMID 40821986, 2025). "LDHA plays a critical role in human cancers owing to its role in promoting glycolysis and converting pyruvate to lactate." (PMID 40782248, 2025). "In view of its vital role in lactate production and the significance of lactate in multiple pathophysiological processes, LDHA has been recognised as a therapeutic target in various types of cancer." (PMID 40629253, 2025). "In hypoxia-induced cancer cells, reduced LDHA expression leads to decreased LDHA activity, lactate production, and intracellular adenosine triphosphate (ATP) levels, significantly inhibiting colony formation and ultimately reducing cancer cell survival." (PMID 40416986, 2025). "Elevated expression of LDHA is commonly correlated with unfavorable prognosis across multiple cancer types." (PMID 41152975, 2025). "Consistent results were shown in another PDAC cell line, SUIT-2, implying that gemcitabine-resistant and cancer stem-like PANC-1 cells have enhanced lactate production due to increased LDHA expression." (PMID 39930542, 2025). "LDH isoforms, particularly LDHA, have been extensively studied due to their critical roles in cancer initiation, progression, metastasis, and angiogenesis." (PMID 40733189, 2025).
cancer (continued). "While this highlights a potential link between nuclear LDHA, redox balance, and proliferation in cancer cells, its relevance and function in cardiomyocytes remain entirely unexplored." (PMID 40710803, 2025). "The overexpression of LDHA leads to increased production and accumulation of lactate, which provides energy and carbon sources for the rapid growth of cancer cells." (PMID 41458606, 2025). "Other factors including lactate, cAMP, estrogen, ErbB2 and HSF-1 have been reported to influence LDHA expression and glycolysis in cancers, indicating that LDHA regulation is subtly controlled by a series of factors that need to be further investigated." (PMID 39930542, 2025). "From the metabolism-related profile by microarray assay, several genes were upregulated in cancer tissues, including LDHA." (PMID 41368023, 2025). "It was shown that the lncRNA LINC0067 has a pivotal role in the STAT3/LINC0067/LDHA axis and is responsible for the suppression of cancer progression." (PMID 40149464, 2025). "High tumoral LDHA/LDHB expression and lactate concentration are associated with cancer progression and poor prognosis in several cancers." (PMID 39796781, 2025). "This indicated that the higher the LDHA level, the earlier the cancer recurrence, the more invasive the cancer, and the shorter the survival time." (PMID 40599233, 2025). "By avoiding OXPHOS, cancer cells primarily use LDHA to redirect pyruvate, a metabolic precursor, toward the pentose phosphate pathway, which promotes the growth of cancer cells." (PMID 41267990, 2025). "Although LDHA nuclear translocation has been documented in certain proliferative cancer cells, where it can enhance antioxidant capacity and support survival under oxidative stress, its role in cardiomyocytes remains poorly understood." (PMID 40710803, 2025). "Aberrant LDHA expression is commonly observed in cancers, and upregulation of LDHA plays an important role in tumorigenesis and malignant progression." (PMID 39930542, 2025). "We highlighted the potential of LDHA as a signal transducer transmitted via EVs to promote cancer aerobic glycolysis and the GSC phenotype." (PMID 40093910, 2025). "Both increasing and decreasing TME lactate have been studied as cancer therapeutic strategies, as demonstrated in the LDHA or MCT inhibitor and Metformin clinical trials." (PMID 40333742, 2025). "Future research should focus on further elucidating the precise mechanisms by which SOX12 and YBX1 regulate LDHA and exploring the potential of the targeting of this axis in other cancer types." (PMID 40593465, 2025). "Lactate dehydrogenase A (LDHA) is a key enzyme in cancer glycolysis that converts pyruvate to lactate and regenerates NAD+." (PMID 40897695, 2025). "The knockdown of LAT1 reduced glycolytic activities via activating PKM2 and LDHA, two key glycolytic enzymes essential for cancer cell growth." (PMID 40611146, 2025). "Although the role of lactate LDHB as a terminal metabolizing enzyme in the glycolytic pathway has been extensively studied in cancer cells, relatively little research has focused on LDHA." (PMID 38829380, 2025). "Certain glycolytic cancer cells (cancers that rely on upregulated glycolysis) can enhance oxidative phosphorylation while suppressing glycolysis, resulting in resistance to LDHA inhibitors." (PMID 40956032, 2025). "It was shown that HULC interacts with LDHA, promoting glycolysis in cancer cells and highlighting HULC’s role in cancer metabolism." (PMID 40861865, 2025). "In response to the central role of LDHA in cancer metabolism, a number of small-molecule inhibitors have been developed to target this enzyme." (PMID 40948941, 2025). "It is also known that inhibitors of LDHA such as oxamate, aminooxyacetate, and dichloroacetate reduce lactate production, thereby decreasing the invasion and migration capabilities of cancer cells." (PMID 40723225, 2025).
cancer (continued). "The upregulation of glycolysis through HIF1α target genes (such as HK2, GLUT1, PDK1, and LDHA) provides cancer cells with rapid ATP production and biosynthetic intermediates." (PMID 39807625, 2025). "There is considerable evidence that LDHA combines with other transcription factors and plays an important role in cancer progression." (PMID 40593465, 2025). "Recent research has identified a novel protein, designated LDHAα, which is 3 kDa larger than LDHA and expresses in various cancer cells." (PMID 41561760, 2025). "Lactate dehydrogenase A, another glycolytic enzyme, is commonly overexpressed in cancer, driving glycolysis and cancer initiation." (PMID 40548063, 2025). "The enzyme lactate dehydrogenase A (LDHA) facilitates the conversion of pyruvate to lactate, allowing cancer cells to regenerate NAD+ and continue glycolysis." (PMID 39997327, 2025). "Under hypoxia or metabolic preference of cancer cells, lactate dehydrogenase A (LDHA) converts pyruvate to lactate, which not only sustains redox balance but also preserves glucose availability for T cells, thereby enhancing antitumor immunity." (PMID 41415548, 2025). "Cancer cells growing in a three‐dimensional environment tend to be more invasive and metastatic, and the activation of LDHA is crucial for these cancer cells to achieve this transformation." (PMID 39778006, 2025). "The interaction between HULC and proteins: Lactate dehydrogenase A (LDHA) and pyruvate kinase M2 (PKM2) are two key enzymes involved in glycolytic reprogramming, a hallmark of cancer that promotes rapid cell growth and survival." (PMID 40909946, 2025). "Inhibition of LDHA expression has been shown to suppress cancer cell proliferation, tumorigenesis, and progression, reduce the expression of CSC markers, and promote apoptosis in lung and colon cancers." (PMID 41368023, 2025). "LDHA is predominantly expressed in cancer cells and favors the conversion of pyruvate to lactate, whereas LDHB is commonly found in non-cancerous cells to promote the reverse reaction from lactate to pyruvate." (PMID 41368023, 2025). "The high expression of STIP1 increased the interaction between AHCY and LDHA and then AHCY recruits PRMT3 to methylate LDHA at R106 to promote the proliferation of cancer cells." (PMID 41163796, 2025). "LDHA expression is significantly upregulated in different cancers and positively correlated with lactate levels." (PMID 41291745, 2025). "In summary, STIP1 acts through AHCY in a moonlighting capacity to post‐translationally activate LDHA and reprogram cancer cell metabolism, fueling ESCC progression." (PMID 41163796, 2025). "Although LDHA activity is typically elevated under hypoxic conditions, cancer cells exhibit aberrant overexpression of LDHA even in normoxic environments." (PMID 40433363, 2025). "Under hypoxic conditions, cancer cells generate lactate via LDHA, and the target genes of c-Myc and hypoxia-inducible factor 1 (HIF-1) encode LDHA." (PMID 40948941, 2025). "We also analyzed the potential correlation between LDHA expression and drug sensitivity in human cancer cell lines." (PMID 38709280, 2024). "We previously showed that genetic deletion of lactate dehydrogenase A (LDHA) in cancer initiating cells of the epidermis led to a marked decrease in the Warburg effect as measured by glucose uptake and lactate production." (PMID 39303037, 2024). "LDHA is highly expressed in many cancers and is a key participant in the progress of cancer (thyroid papillary cancer, prostate cancer, breast cancer)." (PMID 38288377, 2024). "Many proteins identified in exosomes including lactate dehydrogenase A (LDHA), annexin A1/2 (ANXA1/2), or HSP90, are known to be mutated in multiple cancer types." (PMID 38200509, 2024). "Lactate metabolism modulators, particularly lactate dehydrogenase A (LDH-A) inhibitors, show great potential in cancer treatment." (PMID 39654883, 2024).